PGR (progesterone receptor)
Diseases named in the same sentence as PGR in open-access papers (continued):
Sharing a sentence is not in itself a finding about the gene and the disease.
invasive ductal carcinoma (continued). "An invasive ductal carcinoma was diagnosed by core needle biopsy of the lesion and the tumor was estrogen receptor (ER)-negative, progesterone receptor (PgR)-negative, human epidermal growth factor receptor 2 (Her2)-positive (+++), and Ki-67 50%." (PMID 24191208, 2013). "Pathology confirmed an invasive ductal carcinoma, moderately differentiated, 2.4 cm, estrogen/progesterone receptor negative, HER2/neu negative, with negative surgical margins." (PMID 25031990, 2013). "At definitive histology, a G3, ER-negative, PgR-negative, Ki67 = 90%, c-erb-2 negative invasive ductal carcinoma was diagnosed with free tumor margins; each specimen of the medial, lateral, and deep edges of the 4th external intercostal muscle was free from neoplastic infiltration, as well." (PMID 38785498, 2024). "She underwent left mastectomy and axillary node dissection, and a pathological report revealed a diagnosis of infiltrating ductal carcinoma, estrogen receptor (ER)-negative, progesterone receptor (PR)-negative, and HER2-negative (2+ by IHC and FISH negative) by immunohistochemistry (IHC)." (PMID 34135884, 2021). "The patient (III:7) was first diagnosed with an invasive ductal carcinoma of the right mammary gland at the age of 35 (pT1c, N1, G3, estrogen receptor (ER) positive, progesterone receptor (PR) negative, and human epidermal growth factor receptor 2 (HER2) negative)." (PMID 31724318, 2020). "Although these cell lines share mutual characteristics, i.e. both are luminal A (ER-positive, PgR-positive, and HER2-negative), a difference between the cell lines is that the tumor type of MCF-7 cells is metastatic adenocarcinoma, while that of T-47D is invasive ductal carcinoma." (PMID 31768102, 2019). "Invasive ductal breast carcinoma (IDC) is divided into biologically distinct and clinically relevant subgroups on the basis of immunohistochemical status of the estrogen receptor (ER), progesterone receptor (PR), human epidermal growth factor receptor 2 (HER2) and Ki-67 proliferation index." (PMID 31142340, 2019). "The pathologic diagnosis at that time was invasive ductal carcinoma, stage IIA: tumor (T) 2, node (N) 0, metastasis (M) 0, lymphatic invasion (Ly) 0, venous invasion (V) 0, estrogen receptor (ER) (−), progesterone receptor (PgR) (−), human epidermal growth factor receptor 2 (HER2) (−)." (PMID 31870441, 2019). "In addition, more than half of the patients were estrogen and progesterone receptor positive, while mostly included women that were Her-2 negative and 93.1% had invasive ductal carcinoma." (PMID 26958330, 2016). "The histopathological diagnosis was as follows: invasive ductal carcinoma, scirrhous carcinoma, nuclear grade 2, positive for lymph node metastasis (1/16), ER: positive, PgR: negative, HER2/Neu: negative (1+ on immunohistochemistry), Ki67: <5, phenotype: luminal A, pTNM stage: T1cN1M0 stage IIA." (PMID 26943418, 2015). "An incidental right invasive ductal carcinoma was additionally found on review of the pathologic specimen, which was 0.3 cm, grade 1 and strongly hormone receptor positive (estrogen receptor 100%, progesterone receptor 100%) and Her-2/neu negative (IHC score 1+)." (PMID 33507482, 2021). "There was no skin invasion, and core needle biopsy revealed invasive ductal carcinoma cT2N1M0 cStage IIB, estrogen receptor (+)/progesterone receptor (+)/HER2/neu (–)/Ki-67 labeling index: 27.8%." (PMID 39980666, 2025). "Histopathological analysis revealed invasive ductal carcinoma, not otherwise specified (NOS), grade 1, with strong estrogen and progesterone receptor expression (ER+/PR+ >90%), HER2-negative status, and a low Ki-67 proliferation index (10%)." (PMID 40926949, 2025). "Tru-Cut biopsy report revealed invasive ductal carcinoma (IDC) with triple-negative breast cancer (TNBC): estrogen receptor (ER) negative, progesterone receptor (PR) negative, and HER2 negative." (PMID 37124516, 2023).
invasive ductal carcinoma (continued). "Study inclusion criteria are primarily limited to women aged 50 and older with stage I (≤2 cm), estrogen receptor positive (ER+) and/or progesterone receptor positive (PR+), HER2/neu negative, Luminal A subtype, grade I or II invasive ductal carcinoma." (PMID 37629613, 2023). "Most tumors were T1c (40.8%), invasive ductal carcinoma (IDC; 84.1%), histologic grade 2 (49.9%), without lymphovascular invasion (81%), estrogen (ER; 86.1%), progesterone receptor-positive (PR;80.2%), and without HER2 overexpression (88.5%)." (PMID 38132388, 2023). "Core needle biopsy revealed estrogen receptor-negative, progesterone receptor (PgR)-negative, and human epidermal growth factor receptor 2 (HER2)-positive invasive ductal carcinoma of the breast." (PMID 35585439, 2022). "Final histopathology revealed a 9-mm, grade 2, oestrogen receptor-positive, progesterone receptor-negative (ER8, PR0), Her2-negative invasive ductal carcinoma in the right upper outer quadrant, and 4/6 positive lymph nodes (CK7+/CK20−, AE1/AE3+; T1b N2 M0)." (PMID 34781971, 2021). "Most patients were postmenopausal (55.8%) and had invasive ductal carcinomas not otherwise specified (NOS, 81.8%), tumor size >2 cm (69.6%), positive lymph nodes ≥4 (52.0%), ER/PgR-positive (77.7%) and HER2-negative (76.9%) status." (PMID 30063723, 2018). "The final diagnosis was invasive ductal carcinoma with axillary lymph node metastasis (T3N1M1; estrogen receptor negative; progesterone receptor negative; human epidermal growth factor receptor 2 negative; Ki-67 10–20%)." (PMID 26604930, 2015). "The PALB2 truncating mutation c.1653T>A (p.Tyr551Stop) was identified in a woman diagnosed with an infiltrating ductal carcinoma (IDC), negative for estrogen receptor (ER), progesterone receptor (PR) and HER2 at the age of 36." (PMID 23935836, 2013). "In early stage (stages I-III) invasive ductal carcinomas, FRA staining was observed in approximately 30% of all samples, independent of molecular subtype (estrogen receptor (ER)/progesterone receptor (PR)/human epidermal growth factor receptor type 2 (Her2))." (PMID 23961352, 2012). "The biopsy confirmed a pathological diagnosis of invasive ductal carcinoma, no special type (NST), poorly differentiated (G3), estrogen receptor (ER) positive, progesterone receptor (PgR) positive, and HER2-negative, immunohistochemistry (IHC) score = 0, with a Ki-67 proliferation index of 70%." (PMID 39860516, 2025). "Similar pathology was observed in bilateral breast cancer, which showed invasive ductal carcinoma (IDC), categorized as estrogen receptor (ER)-negative, progesterone receptor (PR)-negative, and HER2-positive, with three involved lymph nodes in the right axilla and none in the left axilla." (PMID 38878125, 2024). "A 60-year-old female with no family history of cancer was diagnosed in 2005 with invasive ductal carcinoma of the left breast (cT3N0M0), stage IIB, that was estrogen receptor (ER)-negative, progesterone receptor (PR)-positive and human epidermal growth factor receptor 2 (HER2)-negative." (PMID 35200583, 2022). "An uncomplicated right mastectomy and axillary lymph node clearance was performed: histopathology revealed a 9-mm, grade 2, oestrogen receptor-positive, progesterone receptor-negative (ER8, PR0), Her2-negative invasive ductal carcinoma, and 4/6 positive lymph nodes (T1b N2 M0)." (PMID 34781971, 2021). "She underwent modified radical mastectomy and axillary lymph node dissection, and the final diagnosis was invasive ductal carcinoma with axillary metastasis (T2N3M0; estrogen receptor positive; progesterone receptor positive; human epidermal growth factor receptor 2 negative; Ki-67 10–20%)." (PMID 26604930, 2015).
endometriosis (124 papers, 2005 to 2026). The growth of functional endometrial tissue in anatomic sites outside the uterine body. "HNF-1b (hepatocyte nuclear factor) overexpression and loss of ER/PR (estrogen receptor, progesterone receptor) expression were also present in atypical endometriosis as in CCC." (PMID 40364006, 2025). "Uterine progesterone resistance, resulting from reduced expression of the progesterone receptor (PGR) protein, is implicated in the pathogenesis of endometriosis, adenomyosis, and endometrial cancer." (PMID 40867549, 2025). "Endometriosis has been associated with the failure of progesterone receptor to induce genes counteracting estrogen-driven cell proliferation in the secretory phase, i.e. the progesterone resistance." (PMID 38346980, 2024). "Reduced expression of PGR in endometriosis is perceived as evidence and a cause of progesterone resistance." (PMID 37108154, 2023). "Osteopontin is a molecule that is decreased in endometriosis and implicated in infertility, and Progesterone Receptor Gene polymorphism is being studied as a potential target." (PMID 37512022, 2023). "Previous studies have shown that progesterone receptor resistance is associated with endometriosis development and persistence." (PMID 35576870, 2022). "Among transcription factors responsible for uterine function, HOXA10 is widely known to be associated with endometrial receptivity and progesterone receptor expression, and is hypermethylated in patients with endometriosis." (PMID 36359004, 2022). "Patients with endometriosis have altered progesterone signaling mechanisms and general progesterone receptor deficiency." (PMID 36294778, 2022). "The role of miR-196a was also functionally associated with reduced expression of progesterone receptor isoforms in endometriosis." (PMID 34638843, 2021). "In summary, we were interested to evaluate the correlation between the differential expression of PR isoforms via +331G/A promoter polymorphism of PGR in endometriosis." (PMID 31435600, 2019). "One potential molecular cause of P4 resistance is a loss or alteration of PGR expression, which has been documented in endometriotic lesions and eutopic endometrium from women with endometriosis." (PMID 31387263, 2019). "Endometriosis also causes hypermethylation in the promoter regions of the PR (progesterone receptor) and ESR1 (estrogen receptor 1) genes, which are essential for steroid hormone signaling and endometrial function, reducing their expression and impairing endometrial receptivity." (PMID 39311136, 2024). "Abnormal PGR signaling, chronic inflammation, aberrant gene expression, epigenetic alterations, and environmental toxins are considered potential molecular causes of progesterone resistance in endometriosis." (PMID 37108154, 2023). "ClusterB was revealed to be associated with significantly overexpressed VEGFA and VEGFC and, notably, downregulated ESR1 and PGR, which are characteristic biomarkers of endometriosis, indicating that clusterB might be highly linked to endometriosis." (PMID 36672827, 2022). "Moreover, progesterone receptor expression levels are lower in women with endometriosis associated-infertility, whereas estrogen receptor 1 (ESR-1) levels are increased in the mid- secretory phase endometrium of these women compared to controls." (PMID 36387918, 2022). "These inadequate responses to progesterone receptor in endometriosis could be associated with endocrine therapy resistance." (PMID 34202354, 2021). "Decreased progesterone receptor expression and oncogenic mutations may influence the course of less common and rare site endometriosis." (PMID 33743689, 2021). "Endometrial PGR dysregulation causes several reproductive diseases such as endometriosis." (PMID 34681937, 2021). "Resistance to progesterone may contribute to the pathophysiology of endometriosis, and may be caused by aberrant expression of progesterone receptor (PGR)." (PMID 30728052, 2019).
endometriosis (continued). "Disruption of PGR signaling in endometriosis could also be caused by dysregulation of steroid receptor chaperone proteins like FKBP52." (PMID 31387263, 2019). "The loss of progesterone activitycaused by defect in the progesterone receptor and/or an increase in the local estrogen production due to inappropriateexpression of aromatase may cause thepersistence of ER-α in endometriosis patients." (PMID 29334205, 2018). "This abnormal progesterone receptor change may affect the normal decidualization of the endometrium, making the endometrium less receptive, and may be one of the causes of infertility in patients with endometriosis." (PMID 38397379, 2024). "We constructed three distinct m6A patterns, among which there was a subtype highly consistent with significant low expression of ESR1 and PGR, suggesting that the m6A pattern might be highly linked to endometriosis and could help to predict the occurrence of endometriosis and guide timely treatment." (PMID 36672827, 2022). "Lowered expression of ERα observed in endometriosis may predispose to insufficient responsiveness to E2 with respect to progesterone receptor (PR) expression, thus contributing to secondary PR deficiency and P4 resistance, which is typically observed in women with this disorder." (PMID 33411206, 2021). "Indeed, progesterone receptor (PR) down-regulation is crucial for cell-signaling and cytokine expression in mice, and failure of PR down-regulation is associated with luteal phase defects and endometriosis in women." (PMID 33193109, 2020). "The method was applied using FFPE endometriosis tissue, targeting estrogen receptor alpha (ERα), progesterone receptor (PR), α-smooth muscle actin (αSMA), CD20 and CD31." (PMID 42193044, 2026). "Progesterone resistance, in part mediated by lower levels of progesterone receptor, diminish response to progesterone in endometriosis." (PMID 40457415, 2025). "In our data, PGR expression is low in stromal cells of endometriosis lesions with significant individual heterogeneity." (PMID 39968688, 2025). "PGR, a key hormone receptor in endometriosis, regulates cell proliferation and apoptosis, contributing to disease progression." (PMID 41492385, 2025). "The participation of DNA methylation in the regulation of PGR isoforms expression was described in the “Hormonal Signaling, Dysregulation and Impaired Decidualization in Endometriosis” section." (PMID 40072055, 2025). "In the eutopic endometrium of endometriosis patients, decreased PGR expression correlates with reduced MLL1 levels, resulting in diminished H3K4me3 enrichment at promoters of decidualization-related genes." (PMID 40072055, 2025). "Experimental and clinical data in endometriosis suggest that chronic inflammation can promote progesterone resistance and a relative estrogen-dominant milieu via altered progesterone receptor signaling and NF-κB–driven pathways." (PMID 41463059, 2025). "Epigenetic changes are thought to be responsible for reduced expression of progesterone receptor and homeobox genes in endometriosis." (PMID 38451875, 2024). "It has been shown that aberrant expression of the estrogen receptor (ER) and the progesterone receptor (PR) plays an important role in the pathogenesis of endometriosis." (PMID 39457531, 2024). "Our findings demonstrate that thymol treatment leads to increased PGR expression at both the protein and mRNA levels, providing further evidence that thymol impacts endometriosis via rebalancing the estrogen and progesterone signaling." (PMID 39684860, 2024). "A previous study reported that both miR-196a and MEK/ERK signaling are upregulated in the eutopic endometrium of women with minimal or mild endometriosis leading to the downregulation of PGR expression." (PMID 38813329, 2024). "Our results show a strong coupling of GATA2 and PGR expression levels in the stromal and glandular elements of normal endometrium, which is lost in endometriosis and EAH/EIN." (PMID 39443360, 2024).
endometriosis (continued). "We further correlated the relationship between GATA2 and PGR on a case-by-case basis in endometriosis." (PMID 39443360, 2024). "The aim of this study was to investigate the expression of selected miRNAs, estrogen receptor (ER)α, ERβ, progesterone receptor (PR)-A and PR-B and to determine the target genes of upregulated miRNAs in endometriosis." (PMID 39457531, 2024). "The current key drug for endometriosis is dienogest, a progestin with high specificity for the progesterone receptor." (PMID 36752987, 2023). "They found that KRAS mutations are more frequent in cases of adenomyosis with co-occurring endometriosis, low progesterone receptor expression, or dienogest pretreatment." (PMID 37834773, 2023). "Previous studies have reported that the decreased ESR1/ESR2 in ectopic lesions leads to the decreased expression of PGR, which can exacerbate the inflammatory response, thereby contributing to endometriosis." (PMID 36860677, 2023). "The proteins targeted by these hormones, including progesterone (PGR) and oestrogen receptors (ER), have been shown in endometriosis lesions and their expression is influenced by the microenvironment and associated with treatment response." (PMID 37996888, 2023). "What's more, both AR and PGR were identified as the hub genes between normal endometria and those of endometriosis patients, and ESR1 was selected as the hub gene between eutopic and ectopic endometria from the same patients." (PMID 36860677, 2023). "Endometriosis can occur possibly via a decreased P4 response, and some patients with endometriosis show P4 resistance even with normal PGR expression." (PMID 37270588, 2023). "These discrepancies have been attributed to possible differences in experimental methods, endometriosis subtypes and cell types analyzed, and resolution of PGR isoforms." (PMID 36830705, 2023). "In the eutopic endometria of endometriosis patients, AR, progesterone receptor (PGR) and progesterone receptor membrane component 1 (PGRMC1) showed decreased expression compared with normal endometria, with log2FC<1 in both the GSE51981 and GSE120103 datasets." (PMID 36860677, 2023). "The network of the DEGs between normal endometrium and those of patients with endometriosis contained 683 nodes and 5105 edges, with AR, PGR and PGRMC1 involved in the network construction." (PMID 36860677, 2023). "Many published studies have assessed the expression of PGR in ectopic endometriosis lesions and eutopic endometrium in women with endometriosis." (PMID 37108154, 2023). "Progesterone resistance in the endometriotic lesions of women with endometriosis which results from decreased progesterone receptor (PGR) expression and dysregulation in PGR signaling mediators, has been widely accepted." (PMID 36865552, 2023). "The regulation of these genes, especially ESR1 and PGR, is known to induce estrogen-dependent inflammation and progesterone resistance in endometriosis patients." (PMID 36672827, 2022). "One of the specific pathophysiological mechanisms in endometriosis is progesterone resistance, which is determined by changes in the progesterone receptor (PR) composition." (PMID 36294778, 2022). "The putative role of these miRNAs in modulating PGR expression, progesterone signaling and events conducive to the pathophysiology of endometriosis is discussed in the following paragraphs." (PMID 35406659, 2022). "In accord with these findings, the assessment of progesterone responsive genes in eutopic endometrial tissue from women with endometriosis also revealed that the PGR transcript was increased compared to controls." (PMID 35406659, 2022). "In endometriosis, imbalance of sexual hormones with decreased progesterone and altered expression of the progesterone receptor leads to decreased expression of progesterone-responsive genes, including HOX genes in the eutopic endometrium." (PMID 35273494, 2022).